MSTN (myostatin)
Diseases named in the same sentence as MSTN in open-access papers (continued):
Sharing a sentence is not in itself a finding about the gene and the disease.
diabetes (continued). "With this study, we sought to evaluate whether pharmacologic inhibition of myostatin with a myostatin inhibitory antibody (REGN647) improves muscle and bone mass, as well as muscle and bone strength, in a mouse model of insulin‐deficient diabetes." (PMID 38025035, 2023). "Fibrosis correlated with myostatin (p = 0.025; β-coefficient = 0.464), independent from age, BMI, diabetes mellitus, statin therapy, and other histological characteristics of LV, explaining approximately 40% of its variance (R2 0.413) (data not shown in the table)." (PMID 37958492, 2023). "We investigated whether pharmacologic myostatin inhibition in a mouse model of insulin‐deficient, streptozotocin (STZ)‐induced diabetes is protective for bone and skeletal muscle." (PMID 38025035, 2023). "The pharmacological inhibition of myostatin directly or via decoy receptors has revealed improvements in muscle and bone properties in mouse models of osteogenesis imperfecta, osteoporosis, osteoarthritis, Duchenne muscular dystrophy, and diabetes." (PMID 33854530, 2021). "In our study, kidney MSTN expression was neither related to the diabetes duration nor to HbA1c, while it was directly associated with serum C-reactive protein (CRP) levels." (PMID 32286342, 2020). "In analogy with the finding that high IL-6 upregulates MSTN in muscle, diabetes-induced low grade inflammation might upregulate MSTN in circulating cells." (PMID 32286342, 2020). "In our study, MSTN was expressed more in tubulointerstitial infiltrating cells in diabetic kidney disease compared to nondiabetic proteinuric diseases, suggesting that the kidney MSTN response is induced by diabetes per se." (PMID 32286342, 2020). "Consequently, we confirmed reduced activity of mTOR signaling components and higher expression of atrophy-related markers typified by FoxO1/atrogin-1/MuRF1 and myostatin-Smad2/3 signaling during the course of diabetes." (PMID 30510624, 2018). "This suggests that the therapeutic use of MDSC for muscle repair in CLI in diabetes, or even stem cells in general, may be improved by concurrent anti-myostatin approaches." (PMID 28217409, 2016). "We hypothesized that patients with diabetes and metabolic syndrome may have lower myostatin levels based on the “accelerator-brake” model." (PMID 25254550, 2014). "Here we characterize alterations in the biomechanical responses of bones from PPARβ−/− mice and identify new molecular targets, namely PPARγ and myostatin, that may contribute to the impairment of the muscle and bone functions in diabetes." (PMID 25279796, 2014). "By blocking MSTN action, these inhibitors could enhance muscle growth, increase energy expenditure, and improve insulin sensitivity, offering a promising approach to combating diabetes-related health conditions." (PMID 39340593, 2025). "Additionally, myostatin levels were higher in patients with diabetes than those without diabetes, and low myostatin levels were associated with metabolic syndrome." (PMID 35010726, 2022). "In addition to its influences on protein metabolism, MSTN has many effects on glucose metabolism, and may participate in the pathophysiology of diabetes mellitus." (PMID 32286342, 2020). "According to our results for the MSTN/Akt signaling pathways, both the protein and mRNA expression of MSTN in muscles were decreased by LIPUS in diabetes rats, indicating that the inhibition of MSTN may contribute to improvements in T1DM-induced skeletal muscle atrophy." (PMID 29273088, 2017). "Muscle aging (Atrogin 1 and Glb1), diabetes (RAGE and CD163), and intracellular lipid accumulation (CD36 and PPARγ) related mRNA and protein expressions and FMOD were analyzed in MSTN knockout gas muscles." (PMID 34440852, 2021). "This is contrary to what has been observed in diabetic rats where no change in myostatin transcripts was observed with streptozotocin-induced diabetes or insulin treatment." (PMID 40575255, 2025).
diabetes (continued). "In our study in AS patients, myostatin emerged as a significant predictor of ventricular fibrosis, independent of age, gender, BMI, diabetes mellitus, statin therapy, apoptosis, PLIN5, and ceramides, explaining approximately 40% of the variance." (PMID 37958492, 2023). "The concentration of MSTN in the serum depends on nutritional status—reduced levels have been found in people suffering from anorexia nervosa while increased levels have been observed in obese people or people with metabolic syndrome, T2DM, or pre-diabetes." (PMID 35330038, 2022). "The circulating levels of irisin and myostatin did not significantly differ among subgroups of patients with acromegaly divided according to prediabetes, diabetes, hypercholesterolemia, and atherogenic dyslipidemia." (PMID 34795636, 2021). "Serum myostatin was significantly elevated in adults with type 1 diabetes compared to matched persons without diabetes." (PMID 32652899, 2020). "To identify the triggers by which diabetes can upregulate MSTN in the kidney, we grew HK-2 cells in normal (5 mmol; NG) or high (30 mmol) glucose (HG)." (PMID 32286342, 2020). "A study in humans with or without diabetes found an association between myostatin and the HOMA-IR, though only among participants without diabetes, and only at the gene expression level, not for the circulating protein." (PMID 29445355, 2018). "On the other hand, there is a growing interest in the study of myokines, in particular myostatin, as therapeutic targets for the treatment of skeletal muscle wasting/atrophy under diverse clinical settings, including denervation, AIDS, cancer, diabetes, and chronic heart failure." (PMID 28459069, 2017). "Due to its potent role in skeletal muscle development and its additional direct action on bone, inhibiting myostatin in T1D might help ameliorate the negative effects of diabetes on both muscle and bone." (PMID 40575255, 2025). "Studies suggest that MSTN may promote the progression of obesity and diabetes through its effects on skeletal muscle and other non-muscle tissues (adipose tissue, liver)." (PMID 38398421, 2024). "This reviewsummarizes the potential roles of myokines such as myostatin, irisin,brain-derived neurotrophic factor, mitsugumin 53, meteorin-like, and apelin invarious CVD, including myocardial infarction, heart failure, atherosclerosis,hypertension, and diabetes." (PMID 39077334, 2024). "In contrast, Myostatin serum levels were comparable between patients on regular hemodialysis and patients with or without diabetes mellitus, while patients with liver cirrhosis showed a trend towards higher Myostatin levels compared to non-cirrhotic patients (p = 0.081)." (PMID 32784522, 2020). "Given the potential but still unknown influence of myokines on nutrient and energy metabolism, we aimed to evaluate the association of circulating levels of myostatin, myonectin, and FGF-21 with whole-body IR in individuals without known diabetes mellitus." (PMID 29445355, 2018). "Taken together, the 3wHF diet, with continuous weigh gain even through the final week of the diet and modestly, but non-significantly, increased insulin and myostatin levels, establishes a model to test the effects of rapid weight gain in the absence of overt diabetes." (PMID 26539241, 2015). "They proposed that other factors could probably overrule the negative effect of myostatin on metabolism in patients with diabetes." (PMID 25254550, 2014).
Hyperammonemia (49 papers, 2016 to 2025). An increased concentration of ammonia in the blood. "The authors suggested that higher blood levels of myostatin in patients with cirrhosis were associated with muscle loss, hyperammonemia, and impaired protein synthesis, which was reflected in low serum albumin concentration." (PMID 39590820, 2024). "In the liver–muscle axis, hyperammonemia induced by liver dysfunction causes an increase in the muscular myostatin level." (PMID 37240190, 2023). "Among the liver cirrhosis patients, those having higher serum myostatin concentrations exhibit a poor survival rate, and high serum myostatin concentrations are associated with muscle loss with hyperammonemia to suppress protein synthesis." (PMID 35159148, 2022). "Hyperammonemia mediates the activation of p65-nuclear factor kappa B (NF-kB) which is associated with the transcriptional upregulation and increased expression of myostatin." (PMID 32731496, 2020). "Previous studies in mammalian and avian species have linked hyperammonemia to changes in myostatin expression." (PMID 32722004, 2020). "It was shown that hyperammonemia caused by impaired hepatic function is associated to an increase in MSTN levels and a reduction in muscle mass." (PMID 31044074, 2019). "Myostatin was related in that study with muscle mass loss and hyperammonemia." (PMID 36769301, 2023). "Hyperammonemia was observed in patients with primary carnitine deficiency and could cause muscle atrophy via upregulation of myostatin, which suppressed muscle synthesis." (PMID 34400736, 2021). "In our previous report, we demonstrated that elevated serum myostatin level can be associated with hyperammonemia (correlation coefficients; r = 0.5856 in males and r = 0.3922 in females), hypoalbuminemia (correlation coefficients; r = −0.3844 in males and r = −0.3945 in females), and poor outcomes." (PMID 32722100, 2020). "However, elevated myostatin shows inconsistent associations: some studies link it to muscle loss, hyperammonemia, reduced protein synthesis, and lower liver stiffness, whereas others report that higher serum myostatin predicts poorer prognosis in liver cirrhosis by promoting collagen synthesis." (PMID 41515940, 2025). "In addition to lifestyle factors, alterations to key catabolic molecular pathways (e.g., increased myostatin), impaired mitochondrial function, accelerated starvation, amino acid deprivation, chronic inflammation and hyperammonemia are all suggested to contribute to muscle loss in ESLD." (PMID 37166422, 2023). "Previously, hyperammonemia was reported to result in mitochondrial dysfunction and oxidative stress in skeletal muscle with myostatin upregulation via NF-κB pathway." (PMID 41270090, 2025). "Hyperammonemia transcriptionally activates the synthesis of myostatin in cirrhosis by triggering the translocation of the nuclear factor kappa-light-chain-enhancer of activated B cells." (PMID 37240190, 2023). "Hyperammonemia, a common feature of LC, has the potential to increase myostatin activity and impair mitochondrial function." (PMID 37011140, 2023). "Myostatin seems to be the mediator of hyperammonemia in the inhibition of protein synthesis and the activation of autophagy, being the connection between liver dysfunction and sarcopenia." (PMID 37571424, 2023). "Taken together, LC can reduce the myostatin level through direct pathways like activating the IGF‐1 pathway or decreasing hyperammonemia." (PMID 37078370, 2023). "Muscle hyperammonemia results in increased myostatin expression and decreased activation of nuclear factor kappa B (Nf-B)." (PMID 38255652, 2023). "Hyperammonemia appears to be an important inducer of sarcopenia by affecting the increase in myostatin." (PMID 38255652, 2023). "Hyperammonemia activates in the skeletal muscle the expression of myostatin, a member of the transforming growth factor beta (TGF-β) superfamily produced by myocytes." (PMID 37571424, 2023).
Hyperammonemia (continued). "It has also been widely demonstrated that hyperammonemia leads to increased activation of myostatin in cirrhotic patients, inhibiting protein synthesis." (PMID 35160063, 2022). "Myostatin mediates the effects of hyperammonemia on the inhibition of protein synthesis and the activation of autophagy, being the link between liver dysfunction and sarcopenia." (PMID 36555953, 2022). "Further, hyperammonemia secondary to severe liver dysfunction results in muscle atrophy through the upregulation of myostatin." (PMID 36618679, 2022). "The main focus of this study was to examine the effects of increasing levels of ammonia on myogenesis and myostatin expression in mammalian and avian species, and to examine the myogenic response to hyperammonemia in fish." (PMID 32722004, 2020). "Avian species, however, had a positive myogenic response to hyperammonemia, with a decrease in myostatin expression." (PMID 32722004, 2020). "In avian species, hyperammonemia increased glutamine production in skeletal muscle, and as a result, suppressed myostatin expression as compared to mammals." (PMID 32722004, 2020). "Along this line, the hyperammonemia-myostatin axis has been described as one responsible for muscle wasting." (PMID 33113850, 2020). "Hyperammonemia has been demonstrated to elevate muscle myostatin expression via TLR-independent nuclear factor kappa beta activation in an animal model." (PMID 32722100, 2020). "Examining the relationship between ammonia levels in fish and myostatin expression, and the resultant effects on skeletal muscle, will also increase the current understanding of the role of this protein in the effects of hyperammonemia." (PMID 32629824, 2020). "Decreased protein synthesis and increased protein degradation is the cornerstone mechanism to muscle loss, among others mediated by disease- and inflammation-mediated metabolic changes, hyperammonemia, increased myostatin and reduced human growth hormone." (PMID 32731496, 2020). "In contrast to hyperammonemia induced by cirrhosis, MSTN, the powerful regulator in the muscle physiology, appears not the key factor for regulating muscle metabolism during aerial ammonia exposure." (PMID 31861338, 2019). "Previous studies have demonstrated that hyperammonemia due to malfunctions of the liver, up-regulates MSTN expression in the skeletal muscle." (PMID 31861338, 2019). "We have previously reported that hyperammonemia in LC patients correlated with a higher serum myostatin level, which strongly suppresses skeletal muscle growth." (PMID 31480612, 2019). "Hyperammonemia and reactive oxygen species also act through NF-κB to induce myostatin expression in mouse myoblasts." (PMID 28742154, 2017). "Hyperammonemia, which occurs from impaired hepatic ureagenesis, activates myostatin in chronic liver disease via an NF-κB-mediated mechanism." (PMID 27655344, 2016). "Surprisingly, in broilers embryos, the induced hyperammonemia model showed lower myostatin expression." (PMID 27611572, 2016). "Second, as a common complication of patients with ACLF, hyperammonemia may reduce muscle protein synthesis by upregulating myostatin production." (PMID 41164369, 2025). "Reduces hyperammonemia and myostatin levels, improving muscle protein synthesis." (PMID 39796612, 2025). "Additionally, hyperammonemia in cirrhosis activates the expression of myostatin in skeletal muscle, leading to the inhibition of protein synthesis and the activation of autophagy." (PMID 37571424, 2023). "In addition, hyperammonemia (a factor able to increase myostatin secretion) is related to liver dysfunction." (PMID 36769301, 2023). "A mounting number of studies have unveiled that skeletal muscle mass loss was associated with pathophysiological alternations in the body, including decreased hepatic glycogen synthesis, hyperammonemia, glycogenolysis, myostatin, autophagy, and proinflammatory cytokines as well as endocrine changes." (PMID 35879734, 2022).
Hyperammonemia (continued). "Although the effect on skeletal muscle is less studied, hyperammonemia could activate the expression of myostatin, a member of the transforming growth factor-beta (TGF-β) superfamily." (PMID 36555953, 2022). "Since myostatin appears to have similar functions in both fish and mammals, one hypothesis is that the effects hyperammonemia has on mammalian muscle would mirror those in fish muscle." (PMID 32629824, 2020). "Their research revealed that hyperammonemia stimulated MSTN expression in murine models, and maybe in a NF-κB-dependent manner." (PMID 27611572, 2016). "Indeed, hyperammonemia enhances proteolysis and autophagy, at the same time suppressing protein synthesis in muscles via myostatin signaling and phosphorylation of eukaryotic translation initiation factor 2α, as well as diminished α-ketoglutarate and leucine levels." (PMID 41270090, 2025). "Consumption of alcohol may result in dysbiosis and autophagy of the gut microbiota-induced hyperammonemia, which initiates the up-regulation of muscle protein breakdown and the down-regulation of muscle protein synthesis by activating myostatin, AMPK, and REDD1, and deactivating IGF-1." (PMID 38001472, 2023). "Ammonia-lowering therapy decreased expression of myostatin, autophagy markers and reversed GCN2/eIF2α phosphorylation as well as mTORC1 signaling which were altered by skeletal muscle hyperammonemia." (PMID 31392488, 2019). "NF-κB-mediated upregulation of myostatin has also been observed in other model systems, such as H2O2-treated cultured myoblasts and mouse models of liver cirrhosis and hyperammonemia." (PMID 28742154, 2017). "In the hyperammonemia state, myostatin was suggested to inhibit protein synthesis not through the UPP system but via autophagy-mediated proteolysis." (PMID 33807573, 2021). "Previous studies found that acetic acid and sodium acetate did not alter myostatin expression in murine myotubes, and any effects on gene expression are due to the hyperammonemia." (PMID 32722004, 2020). "Hyperammonemia leads to the transcriptional upregulation of myostatin, a TGFβ super-family member, and studies in differentiated murine myotubes exposed to ammonia or in muscle from hyperammonemic PCA rats, myostatin expression was likewise increased." (PMID 31183339, 2019). "Although hyperammonemia was reported to upregulate MSTN and inhibit downstream mTOR pathway, no changes have been found in the mRNA expression level of MSTN and protein expression level of mTOR signal pathway after ammonia exposure." (PMID 31861338, 2019). "During hyperammonemia, ammonia which has not been converted into glutamine activates the NF-κB pathway to up-regulate myostatin (MSTN) expression in the myocyte." (PMID 31861338, 2019). "However, a direct link has not been reported between hyperammonemia or myostatin and the TGR5 receptor." (PMID 33113850, 2020).